RNU1-107P (RNA, U1 small nuclear 107, pseudogene)
Gene: Small nuclear RNA gene on chromosome Y (25,723,342 to 25,723,495, forward strand). Ensembl gene ENSG00000252426.
Homologues: Orthologues: macaque U1 (78% identical). Paralogues in human: RNU1-86P (100% identical), RNU1-41P (81% identical), RNU1-48P (81% identical), RNU1-128P (80% identical), RNU1-95P (80% identical), RNU1-40P (79% identical), RNU1-97P (79% identical), RNU1-1 (78% identical), RNU1-2 (78% identical), RNU1-27P (78% identical), RNU1-28P (78% identical), RNU1-3 (78% identical), and 134 more.